EGFR (epidermal growth factor receptor)
Diseases named in the same sentence as EGFR in open-access papers (continued):
Sharing a sentence is not in itself a finding about the gene and the disease.
tumor (continued). "Finally, the secreted TGFα activates the EGFR/Raf/MEK/ERK signalling pathway, enhancing tumor cell proliferation." (PMID 26300397, 2015). "The distribution of observed mutations was consistent with prior reports: 50% (19 of 38 patients) had a KRAS mutant tumor, 16% (6 of 38 patients) had a PIK3CA mutation, 8% (3 of 38 patients) showed a mutation in BRAF, and none showed an EGFR mutation." (PMID 25575824, 2015). "rAd-ASPP2 treatment significantly inhibited tumor growth, but treatment with rAd-ASPP2 combined with ne-EGFR was a more powerful inhibitor of transplanted tumor growth than rAd-ASPP2 treatment alone or rAd-ASPP2 combined with erlotinib because ne-EGFR extended and amplified ASPP2-induced apoptosis." (PMID 25980493, 2015). "In cultured tumor cells SFK activation was not only EGFR independent, it was constitutive (in absence of serum)." (PMID 25779657, 2015). "Gold nanoparticles have been used as a micro-CT contrast agent for the targeting of multiple tumor markers, including Her2, the gastrin-releasing peptide (GRP) receptor, the epidermal growth factor receptor (EGFR), the folic acid receptor (FAR), and tumor microcalcifications." (PMID 26581654, 2015). "Likewise, overexpression of miR-203 was shown to enhance the effect of another EGFR-targeting TKI, CI-1033, and to reduce tumor size in a xenograft model of RAS-driven cells." (PMID 26287249, 2015). "Among the other two hub genes both with high degree of 16, EGFR has been among the most important prognostic factors for HNSCC, while the kinase PDGFRB was found to be up regulated in tumor indicating the effectiveness of tyrosine and serine-threonine kinase inhibitors in the treatment of HNSCCs." (PMID 26064958, 2015). "Here we assessed whether the combination of two therapeutic monoclonal antibodies, cetuximab, and IMC-A12 that specifically target EGFR and IGF-1R, respectively, would enhance HNSCC tumor response to radiation." (PMID 25355701, 2015). "Blockade of STAT3 pathway synergistically increased anti-tumor activity of gefitinib, as well as another EGFR inhibitor (erlotinib) (data not shown)." (PMID 25928246, 2015). "Frequency distributions of mutations within exons 18–21 of EGFR in morphologically not acceptable, acceptable and dataset NSCLC-derived tumor specimens." (PMID 25844806, 2015). "The development of subsequent LM in patients on treatment with an EGFR-TKI is felt to be a pharmacokinetic failure, wherein the penetration of EGFR-TKI into the cerebrospinal fluid is inadequate to suppress leptomeningeal tumor involvement." (PMID 25784657, 2015). "Compared to the non-targeted nanoparticles, the epidermal growth factor receptor (EGFR) targeted nanoparticles showed significantly more effective tumor shrinkage after magnetic hyperthermia treatment." (PMID 26021823, 2015). "Currently, the role of EGFR in tumor development in ESCC is not clear, although elevated expression of EGFR has been reported in 50–90 % of patients with ESCC." (PMID 26338103, 2015). "It is not unusual to observe amplification of both wild-type EGFR and EGFRvIII in the same tumor; EGFRvIII is rarely observed in isolation." (PMID 26423602, 2015). "EGFR activation in human carcinoma cell lines also increases matrix metalloproteinase-9 (MMP-9) activity, which increases in vitro cell invasion by facilitating disintegration of ECM barriers to tumor invasion." (PMID 26635612, 2015). "No previous study has provided a classification for EGFR copy number in EC to the degree that has become routine practice in other tumour types." (PMID 26478746, 2015). "Additionally, western blot analysis showed significant increases in the phosphorylation levels of EGFR, c-Raf and ERK1/2 in tumours compared with normal tissues." (PMID 26300397, 2015).
tumor (continued). "In addition, the correlation between COX-2 and the EGFR pathway in tumorigenesis has been demonstrated, suggesting that combination therapy with COX-2 and EGFR inhibitors would be more effective in tumor suppression than either agent alone." (PMID 25595899, 2015). "In addition to driving TNBC tumor formation, BRCA1-IRIS overexpression drives their intrinsic and acquired paclitaxel resistance, partly by activating autocrine signaling loops EGF/EGFR-ErbB2 and NRG1/ErbB2-ErbB3." (PMID 25583261, 2015). "There is little chance that this observation might be due to the tumor sample volume because the ARMS approach has a well-known detection sensitivity, and the EGFR M+ frequency according to biopsy sites was comparable." (PMID 26599344, 2015). "LeY antibody (IGN311) inhibited EGFR-mediated MAPK signaling activation and prevented tumor growth." (PMID 25672851, 2015). "To generate adenoviral vectors with improved tumor specificity, we generated a panel of Ad5 vectors with altered tropism for EGFR and FGFR, rather than the natural Ad5 receptor, hCAR." (PMID 25919378, 2015). "In addition to tumor subtype, the significant prognostic factors were age, tumor size, tumor location, venous tumor emboli, nervous invasion, serosa invasion, lymph node metastasis, TNM stage, and EGFR expression." (PMID 26642199, 2015). "Tumor cell budding, defined as invasion by single tumor cells or small clusters of cells at the leading edge, is an independent adverse prognostic factor in CRC and predicts response to antiepidermal growth factor receptor (EGFR) therapy." (PMID 26106602, 2015). "In this study, we investigated candidate determinants of resistance related to the immune tumor microenvironment and inflammatory response, using as proof of principle two mainstay of first line treatment for metastatic CRC anti-EGFR cetuximab, anti-VEGF bevacizumab based therapy." (PMID 26427914, 2015). "These facts and background encouraged us to examine the anti-tumor effect of TAE226 in NSCLC, and we unexpectedly found that TAE226 preferably inhibits the proliferation of EGFR-mutant NSCLC cell lines including the T790M mutant, compared with EGFR-wild-type NSCLC cell lines." (PMID 26090892, 2015). "To determine the status of active EGFR/HER and active KRAS/pan-RAS levels across all treatment groups, we performed both immunoblot analysis and a Raf ‘pull down assay’ on cell lysates extracted from crude tumor tissue." (PMID 25992771, 2015). "Further, the low percentage of tumor cells did not preclude effective EGFR analysis using real-time PCR techniques." (PMID 25086987, 2015). "One patient whose primary tumor harbored an exon 19 deletion had received a prior EGFR-TKI as maintenance therapy in the setting of having no evaluable disease; therefore, it was impossible to assess response to prior EGFR-TKI in that patient." (PMID 25784657, 2015). "Our study indicates that sensitivity of tumor cells to cytotoxic agents in general does not change before and after failure of EGFR-TKIs." (PMID 25875914, 2015). "Treatment with 0.02 mg/kg tunicamycin for 21 days resulted in significant decrease of EGFR, HER2 and HER3 in tumor samples from MCF-7/HER2 xenograft, demonstrating that the dose of 0.02 mg/kg tunicamycin abrogated the N-glycosylation process in tumor." (PMID 26498681, 2015). "Up-regulated genes EGFR and HMGA2 are possible tumor markers of OSCC." (PMID 26179909, 2015). "The patient’s age, tumor grade, and EGFR of the primary tumor were not different between the ILCs and IDCs." (PMID 25889560, 2015). "In contrast, CH12 targets a cryptic epitope of EGFR or EGFRvIII, which only exposes in tumor cells and not in normal tissue, leading to a good safety profile." (PMID 26474285, 2015).
tumor (continued). "In conclusion, we found that TAE226 inhibited the activation of EGFR-mutant kinase and exerted anti-tumor activity on EGFR-mutant NSCLC regardless of the presence of T790M mutation." (PMID 26090892, 2015). "Twice daily dosing might produce an improved response, as could co-administration of an ABCB1 inhibitor that can achieve intra-tumor concentrations of lapatinib required to maximally inhibit HER2 and EGFR signaling." (PMID 26571496, 2015). "To understand if EGFR mutations can affect RFS, we sequenced the exons 18, 19, and 21 of EGFR in 48 fresh-frozen tumor tissues (data not shown)." (PMID 25806093, 2015). "This mismatch is not novel; previous studies have revealed discordances in EGFR status between the primary tumor and the corresponding metastases in approximately one-third of cases." (PMID 25663915, 2015). "Interestingly, a new regulatory mechanism for EGFR signaling linking inflammatory and tumor-promoting signals in HCC was proposed, as TNF-α was shown to induce AR shedding and therefore EGFR transactivation in HCC cells." (PMID 26729094, 2015). "In addition, we found that the Classical markers FGFR3, PDGFA, EGFR, AKT-2 and Nestin are highly expressed in intracranial tumor tissue derived from bulk tumor cells and Sp-GSCs, while there is lower expression in Ad-GSC intracranial tumors." (PMID 25955030, 2015). "It was recently suggested that drug resistance to anti-EGFR therapies in HNSCC is not affected by the hypoxic tumor microenvironment within the investigated tumors." (PMID 26579120, 2015). "The results showed that although both cell lines were resistant to TMZ treatment, co-treatment of Nimotuzumab and rapamycin was more effective in cell kill when compared to single treatment regardless of the EGFR status of the tumor." (PMID 25886314, 2015). "In summary, we found that MSCs promote the IBC skin phenotype and metastasis independent of tumor initiation and that EGFR inhibition blocks MSC-promoted metastasis in IBC." (PMID 25887413, 2015). "Of those specialists in France who did not test KRAS status, reasons for not testing were that the patient had received prior anti-EGFR-treatment (63% of patients) or there was an absence of tumor/technical issues (27% of patients)." (PMID 26491871, 2015). "To evaluate whether AZD5363-induced feedback to HER receptors was also observed in vivo we analysed phospho and total EGFR, HER2 and HER3 levels at the end of anti-tumour study." (PMID 26095475, 2015). "In previous work, EGFR-targeted NIR-PIT with a repeated regimen was able to cure >80% of highly expressing A431 tumors, so we investigated a split NIR-PIT regimen (total cet-IR700 dose is the same as the one shot NIR-PIT) for MDAMB468 tumor." (PMID 26313651, 2015). "EGFR alterations increase cell signaling through multiple pathways, including the phosphatidylinositol-3-kinase (PI3K)/Akt/mTOR pathway, and ultimately accelerate tumor growth and progression." (PMID 25785247, 2015). "Immunohistochemistry (IHC) showed that tumor cells were positive for epidermal growth factor receptor (EGFR) and ErbB2/HER2, but negative for estrogen receptor (ER) and progesterone receptor (PR)." (PMID 25890325, 2015). "Importantly, genes co-expressed with SLC16A7/MCT2 in human tumours also clustered in oncogenic-related pathways (e.g. PI3K, EGFR, KRAS) and effectors of these signalling pathways were found to bind at the SLC16A7/MCT2 gene locus (e.g. MYC, EGR1, PRDM1)." (PMID 26035357, 2015). "Our results, therefore, suggest that resistance to anti-EGFR therapy in HNSCC is most likely not the result of hypoxic regions within the tumor and, hence, other mechanisms are involved." (PMID 26032726, 2015).
tumor (continued). "Bortezomib, that contributed to clinical response of squamous cell carcinoma of the head and neck (SCCHN), antagonized cetuximab- and radiation-induced cytotoxicity, degradation of EGFR, and enhanced pro-survival signal pathway activation in SCCHN tumor biopsies and in the cell line UMSCC-1." (PMID 26285137, 2015). "In murine models, both antibodies have been shown to enhance priming of anti-tumor CD8+ T cells and increase pro-inflammatory cytokine release; however, in human patients treated with anti-EGFR, the frequency of intratumoral, immunosuppressive Tregs was increased." (PMID 27066495, 2015). "Tumor cells have been shown to develop alternative compensatory pathways to sustain cell proliferation, ultimately leading to drug resistance, such as HER3, IGF-1R, EGFR and insulin receptor pathways." (PMID 25762617, 2015). "We determined EGFR and c-MET expression levels on a panel of 11 tumor cell lines using QFCM." (PMID 26260789, 2015). "Primary tumours from all lines were negative for progesterone receptor, Erb-b2/Neu and cytokeratin 5/6, but positive for epidermal growth factor receptor (EGFR)." (PMID 25633981, 2015). "Current approaches are utilizing EGFR/EGFRvIII as a unique tumor antigen to specifically identify GBM cells rather than targeting the EGFR's biological function and have emphasized the significance of EGFR/EGFRvIII as a target for GBM therapy." (PMID 26136784, 2015). "Long term endocrine therapy is frequently related to upregulation of receptor tyrosine kinases (RTKs) such as EGFR and HER2 as well as the activation of ER to promote endocrine resistant tumor cell proliferation, but details of mechanisms of activation of RTKs and ER were not yet clear." (PMID 26697525, 2015). "Currently, 20–30% of EGFR-mutant NSCLC patients do not undergo tumour shrinkage on treatment with an EGFR-TKI, thus identifying a primary resistant cohort." (PMID 26435742, 2015). "Moreover, the combined treatment of TG101348 and erlotinib induced apoptosis, inhibited the activation of p-EGFR and p-STAT3, and inhibited tumor growth of erlotinib-resistant NSCLC cells in vivo." (PMID 25869210, 2015). "Long-term tamoxifen treatment facilitates translocation of GPER to cell membranes, resulting in aberrant activation of the EGFR/ERK signaling pathway and upregulation of β1-integrin expression which is responsible for the enhanced communications between tumor cells and the tumor microenvironment." (PMID 25990368, 2015). "In addition, we also observed decreased expression of survivin, bcl-2, EGFR and induced PARP cleavage in tumor lysates from nude mice bearing ACHN cells as a xenograft and treated with DIM-C-pPhOH (30 mg/kg/d)." (PMID 26035713, 2015). "Histological analyses of xenograft tumours derived from these cell lines confirmed SCLC histology and expression of neuroendocrine (NE) markers in contrast to xenograft tumours derived from a resistant EGFR mutant cancer that maintained NSCLC histology." (PMID 25758528, 2015). "Though tumor samples exhibited a broad range of cell-surface expression of EGFR, c-Met, and IGF-1R, no cell-surface erythropoietin receptor was detected in tumor cells from the 186 tumors examined (by flow cytometry or Western blot)." (PMID 25807104, 2015). "Still, differences in EGFR expression in tumors per se are most likely not the main determinant of the overall observed differences in [11C]erlotinib tumor uptake." (PMID 25853010, 2015). "Appropriately, co-inhibition of EGFR and c-MET suppressed tumor growth in preclinical models." (PMID 25973541, 2015). "Field effects for DNA methylation changes in RASSF1, EGFR and TFF1 might be important in influencing pre-neoplastic changes in gene expression relevant to tumor development." (PMID 26510686, 2015).
tumor (continued). "In addition, our current study also showed that concurrent radiotherapy with gefitinib is effective in elderly patients with ESCC without EGFR overexpression or mutation, indicating that gefitinib could help to sensitize tumor cells to the effect of radiotherapy." (PMID 26392415, 2015). "We hypothesize that FAK serves as a convergence point for both EGFR and β4 integrin signals, to diversify signaling and to initiate p38MAPK and AKT activity during tumor malignancies." (PMID 26549523, 2015). "The data obtained in this study verified the effect of EFEMP1 in suppressing EGFR-driven cancer cell growth, and demonstrated a new activity of EFEMP1 in suppressing cell type/proportion change within a tumor, thereby maintaining existing intra-tumoral heterogeneity." (PMID 26307682, 2015). "It is not suppressing that not all patients with wild type KRAS in the primary tumor are successfully treated with anti-EGFR antibodies." (PMID 25628770, 2015). "Analysis of baseline tumor RTK profiles revealed that, regardless of EGFR mutation status, higher levels of EGFR relative to MET correlated with longer PFS." (PMID 26439803, 2015). "Another important aspect to highlight in the failure of anti-EGFR targeted therapy are the intra-tumor heterogeneity, acquired resistance to anti-EGFR inhibitors and the non-existence of an established biomarker to predict response to anti-EGFR treatments." (PMID 26267324, 2015). "Though, PDT treated tumors expressed greater EGFR levels, the increase in tumor size was not as significant as the control tumors." (PMID 25918252, 2015). "The basal-like tumor represents a specific group characterized by the expression of genes found in normal basal/myoepithelial breast cells, including high-molecular-weight basal cytokeratins (CK5/6, CK14, and CK17) or EGFR or both." (PMID 25902832, 2015). "In general, the relationships between tumor EGFR gene variation and protein expression have not been clearly defined, and the prognostic value of these tumor characteristics has not been well evaluated for ESCC." (PMID 25953424, 2015). "EGFR further mediated the phosphorylation of the cytoplasmic tail of the transmembrane mucin MUC1 and this enhanced its affinity for β-catenin potentially correlating with a decrease in cell adhesion and an increase in invasiveness of tumor cells." (PMID 26729094, 2015). "Finally, downregulation of cyclin D1, c-MYC, survivin, c-Met, EGFR, Src, FAK, and α-tubulin expression was observed in 786-O tumor xenografts treated with ART." (PMID 26426994, 2015). "The expression of the EGFR constructs in the MCF10A cells did not induce primary tumour formation up to 6 months post-injection (data not shown)." (PMID 25969993, 2015). "Thus, it is very difficult to predict the outcomes of EGFR-TKI therapy based on patient and tumor factors alone." (PMID 25888731, 2015). "Several small retrospective studies have identified some clinical factors and molecular biomarkers that are predictors of tumor response to preoperative CRT, including the tumor size, carcinoembryonic antigen (CEA) level, epidermal growth factor receptor, and p21." (PMID 26268466, 2015). "EGFR signaling regulates the proliferation and tumorigenic ability of GSCs by inducing ID3 and ID3-regulated cytokines (GRO1, IL-6, and IL-8), which play a crucial role to make the tumor microenvironment suitable for GSC maintenance." (PMID 26437223, 2015). "ORR was similar in EGFR IHC 0 and 2 + subgroups; there was a possible trend of a correlation between EGFR status and tumor response; however, inference testing was not performed." (PMID 23689990, 2015). "There was no expression of oligodendrocyte transcriptor-2 (Olig-2), epidermal growth factor receptor (EGFR), neurofilament (NF), CD117, nestin or microtubule-associated protein 2 (MAP2) in the tumor cells." (PMID 24348765, 2014).